CD4 (CD4 molecule)
Diseases named in the same sentence as CD4 in open-access papers (continued):
Sharing a sentence is not in itself a finding about the gene and the disease.
tumor (continued). "The higher density of CD4+ and CD8+ T cells were identified in tumor samples of boost vaccinated mice compared to control tumors." (PMID 21067607, 2010). "MDSCs suppress the activation of CD4+ and CD8+ T cells and also facilitate the generation of tumor-specific Tregs." (PMID 21048993, 2010). "Recently, the prognostic value of various tumor-infiltrating CD4+ T-cell populations (CD4+CD25+, CD4+CD69+, and CD4+FOXP3+ T cells) was determined in HNSCC patients." (PMID 21437225, 2010). "Importantly, however, the authors found that antigen presentation by host cells was required at the effector phase for this tumor rejection by primed CD4+ T cells and speculate that this may be through the activation of local macrophages and other cells but never validated this." (PMID 21076522, 2010). "In contrast, AFP-specific CD4 T-cell responses are only detected in HCC patients and response was mainly detected in Okuda tumour stage I HCC patients (58.3%) and to a lesser extent in Okuda tumour stage II or III HCC patients (15.8%)." (PMID 20087354, 2010). "Tumour rejection experiments were also done in Her2MPtVLP immunized normal and CD4−/− and CD8−/− single, as well as CD4−/−CD8−/− double knock-out C57Bl/6 mice." (PMID 20657846, 2010). "Positive CD4, CD3, CD8, CD68 and Foxp3 cells were detected in 33/33 (100%) tumor samples and their mean number were similar between the two patient groups." (PMID 20591136, 2010). "Eight hours after the last BrdU injection, CD4+ T cells and CD8+ T cells were isolated from the tumor mass and analyzed for the incorporation of BrdU." (PMID 20981279, 2010). "It is possible that the activation of both pro-inflamatory CD4+ T-cells and cytotoxic CD8+ T-lymphocytes in adequate proportions leads to an efficient immune response that control the growth of tumor cells." (PMID 20525350, 2010). "Ten days after transfer, the CD4+ T cells and CD8+ T cells were isolated from tumor mass and analyzed for their expression of surface activation marker CD62L and CD44." (PMID 20981279, 2010). "Our studies demonstrate that CD4+ T cells expanded against tumor antigen secrete high levels of CCL5, thus promoting the recruitment of CCR5 expressing T cells and DCs to the tumor site." (PMID 21076522, 2010). "CFSE-stained cells found in the tumor draining lymph nodes on day 3 were 30% CD8+, 72% CD4+, 95% CD44+, and 39% CD69+." (PMID 21050466, 2010). "During maturation DCs migrate from tumor tissues to T-cell-rich areas of secondary lymphoid organs, where they activate tumor-reactive CD8+ cytotoxic T lymphocytes (CTLs) and CD4+ T cells." (PMID 21076523, 2010). "Up to now, published studies have used autologous tumour cells as antigenic stimulations, which can lead to polyclonal expansion of specific CD8 and CD4 cells." (PMID 20953324, 2010). "A considerable immunization effect was still observed after CD4+ or CD8+ depletion, since 80% and 90% of the mice respectively stayed tumour-free during the whole observation period (p<0.001 compared to unimmunized mice in both cases)." (PMID 20657846, 2010). "These investigators further demonstrated that CD4+ T cells, CD8+ T cells, or a combination of both, derived from DTA-1 treated tumor-challenged mice, led to tumor rejection following adoptive transfer in their model system." (PMID 20936139, 2010). "Using exclusively primary human CD4+ T cells we found a correlation between over-expression of PGE2 in tumor cells and tumor-induced CD4+ T cell apoptosis." (PMID 19812686, 2009). "Finally, CD4 T cells, in some cases, themselves, may be cytotoxic to tumor cells." (PMID 19707583, 2009). "The Kupffer, NK, NKT, CD4+ T, and CD8+ T cells are activated, but CD8+ T cells are the major effector cells to kill the tumor cells, whereas the CD4+ T cells have an effector function as well as a regulatory function." (PMID 19272170, 2009).
tumor (continued). "Among tumor-bearing mice, those treated with liqi had consistently higher percentages of CD3+CD4+ T lymphocytes than did untreated mice (P < 0.05)." (PMID 19570195, 2009). "Regulatory T (Treg) cells, a subset of CD4+CD25+Foxp3+ T lymphocytes, are mediators with the functional ability to regulate/suppress tumour immunity." (PMID 19935800, 2009). "DTA-1, an antibody for GITR, can abrogate Treg suppression while not depleting Treg, can reverse Teff/Treg ratio and increase CD4 T cell infiltration into tumors, and can synergize with CTLA-4 blockade to enhance anti-tumor immunity." (PMID 19175928, 2009). "Although many investigators have centred in the activation and targeting of tumour-specific CD8+ CTL and CD4+ T cells are required for the priming and maintenance of CD8+ T cells." (PMID 19277034, 2009). "Experimental studies have outlined the critical role of CD4+ and CD8+ T cells and NK cells in mediating anti-tumor immunity." (PMID 19570195, 2009). "Up to now, most of the tumour vaccines reported were targeting mainly MHC class I. A number of recent studies confirmed, however, that immunizations addressing CD4+ T cells are more efficient than peptide vaccinations targeting only CD8+ cells." (PMID 19738910, 2009). "Tremelimumab was shown not only able to suppress Treg activity, but also to replenish the effector and memory CD4+ and CD8+ T-cell numbers, contributing to its anti-tumour effect." (PMID 19384299, 2009). "Ever since classical T regulatory cells were discovered utilizing CD4+ CD25+ T cell depletion experiments, tumor immunity has been closely examined in regard to Tregs." (PMID 19175928, 2009). "To determine if the increased protection after B7.1-expressing tumor immunization was mediated by a T-cell based immune response, we used mAbs to deplete CD8+ or CD4+ T cells in C57BL/6 mice before immunization and tumor cell challenge." (PMID 19629186, 2009). "CD4+ T cells would then recognize GILT-expressing cells and recruit other immune cells and APCs in order to destroy the tumor cells." (PMID 20016802, 2009). "Previously, we have proposed that tumour-specific CD4+ T cells, especially T-helper type 1 (Th1) cells play a critical role for inducing cytotoxic T lymphocytes (CTL)-mediated antitumour immunity in tumour-bearing mice." (PMID 19277034, 2009). "Activation of OX40, a co-stimulatory molecule belonging to the TNF receptor superfamily, leads to expansion of CD4+ and CD8+ T cells resulting in tumour rejection in murine models." (PMID 19384299, 2009). "Results suggest that protection of mice from tumor challenge fully depended on CD8+ T cells and partially depended on CD4+ T cells." (PMID 19629186, 2009). "It has been confirmed that CD4+ and CD8+ T lymphocytes play important roles in induction of anti-tumor immune." (PMID 19788747, 2009). "CD4+ TH17 cells, that secrete IL-17, have been shown to accumulate in the tumor microenvironment and contribute to the pathogenesis of cancers." (PMID 20017942, 2009). "A final consideration is that, in the present study, autoantibody responses to NY-ESO-1 were correlated with infiltration of tumor by not only CD8+ T cells, but also by CD4+ and FoxP3+ T cells." (PMID 18923710, 2008). "Similar to CD3+ cells, CD8+, CD4+, FoxP3+ and TIA-1+ cells were generally denser in tumor stroma than tumor epithelium." (PMID 18923710, 2008). "Tumor tissue was examined by immunohistochemistry for expression of NY-ESO-1, various T cell markers (CD3, CD4, CD8, CD25, FoxP3, TIA-1 and Granzyme B) and other immunological markers (CD20, MHC class I and MHC class II)." (PMID 18923710, 2008). "Specifically, the presence of NY-ESO-1-specific IgG autoantibodies in serum correlated with infiltration of tumor stroma by cells expressing CD8, CD4 and FoxP3." (PMID 18923710, 2008).
tumor (continued). "These cells, isolated from draining lymph nodes of patients with pancreas orbreast cancer secrete IL-10 and TGF-β, prevent activated CD4+ CD25− and CD8+ effector T cells, and suppress tumor-specific immune response." (PMID 19009040, 2008). "At various time points following treatment the right tumours were removed and examined by flow cytometry for the presence of infiltrating T cells, which were defined as CD45+, CD3+, and either CD4+ or CD8+." (PMID 17505510, 2007). "In these experiments RAG–/– mice were injected with CD4+CD25+ Treg cells or control CD4+CD25– cells, both from naive mice, or PBS alone, followed by B16F10 tumour challenge." (PMID 17294404, 2007). "As reported by us previously, there were substantial increases in the number of CD4+, CD8+, Mac-1+, and GR-1+ cells in the tumor-bearing lungs of mice that received wt effector T cells." (PMID 18001476, 2007). "We recently reported that HVJ-E itself induced a remarkable infiltration of DCs, CD4+ T cells, and CD8+ T cells into tumors and activated tumor-specific CTLs." (PMID 17883878, 2007). "Based on these results, we propose that mIL-18 overexpression in the tumor site induces phenotypic changes in the T cell and B cell subsets, and protects against tumor development by stimulating IFN-γ production by CD4+ T cells." (PMID 17519043, 2007). "Various experimental studies have outlined the critical role of CD4+ and CD8+ T cells and NK cells in mediating anti-tumor immunity." (PMID 17338814, 2007). "To confirm this finding in vivo, we purified CD4+CD25+ cells or CD4+CD25– cells and injected them concomitantly with B16FasL tumour cells into the peritoneum of B6 mice." (PMID 17294404, 2007). "This relationship appeared to result mainly from a decrease in CD4+ T cells and an increase in CD8+ T cells, especially in group B, as the tumor progressed." (PMID 17338814, 2007). "Methylcholanthrene-induced tumours were removed from mice and examined histologically for Tregs by staining sections with Abs specific for FOXP3 and CD4." (PMID 17565340, 2007). "In vivo depletion of NK cells abolished ex vivo tumour lysis by peritoneal lavage cells, as did adoptive transfer of CD4+CD25+ cells, whereas depletion of Treg increased tumour killing." (PMID 17294404, 2007). "CD4 and CD8 cells were isolated and transferred into naïve C57/BL6 mice at the time of tumor challenge." (PMID 16725035, 2006). "A wealth of evidence obtained using mouse models indicates that CD4+CD25+FOXP3+ regulatory T cells (Treg) maintain peripheral tolerance to self-antigens and also inhibit anti-tumor immune responses." (PMID 17205133, 2006). "This CEACAM recognition pattern of scFv E8 was also verified on a large panel of human cells which included 18 tumor cell lines, adult primary fibroblasts, PBMC subpopulations CD4 and CD14 and neutrophils." (PMID 16504122, 2006). "For activation and maintenance of tumour-infiltrating CD8+ T cells, CD4+ T cells play an important role by secreting cytokines such as interleukin-2, which is required for CD8+ T-cell growth and proliferation." (PMID 16421594, 2006). "Tumour-infiltrating T lymphocytes were predominantly observed within the cancer stroma by immunohistochemical staining for CD8 and CD4." (PMID 16421594, 2006). "We utilised the mean number of infiltrating cells as a cutoff point to divide all tumours into groups as having either ‘high’ or ‘low’ infiltration by CD8+ and CD4+ cells in stromal and in nest tissue." (PMID 16421594, 2006). "Thus, HLA-DR*1101-Bir tetramers could be pulsed also with a naturally processed promiscuous tumour-derived peptide, and might prove useful in characterising naturally arising or therapeutically induced CD4+ T cells responses in HLA-DR*1101 patients with tumours expressing MAGE-3." (PMID 16329759, 2005). "In several animal studies, it has been shown that immunization with cancer-antigen loaded DCs efficiently primes both CD4+ and CD8+ T-cells, resulting in protective immunity against tumours." (PMID 15720715, 2005).
tumor (continued). "Tumors can suppress CD4+ T cell activity and CTL tumor lysis directly through secretion of immunosuppressive factors including TGF-β1 but also PGE-2, and IL-10." (PMID 16045800, 2005). "CD4+ and CD8+ T-lymphocyte infiltration of the tumour was assessed using immunohistochemistry and a point counting technique." (PMID 15700032, 2005). "The expectation was that the percent of CD4+CD25+CCR7+ cells would be lower in patients than NC, based on our report documenting an enrichment in Treg at tumour sites and tumour-involved lymph nodes relative to the peripheral circulation." (PMID 15714205, 2005). "Blockade of the inhibitory effects of galectin-1 within tumour tissue resulted in reduced tumour mass (an effect which required intact CD4+ and CD8+ T-cell responses) and stimulated the generation of a tumour-specific T-cell response in vivo." (PMID 15785741, 2005). "In patients with SCCHN, we have recently described a significant enrichment in CD4+CD25+ T cells in the peripheral blood and particularly among tumour-infiltrating lymphocytes." (PMID 15714205, 2005). "Immunohistochemical techniques were used to determine lymphocytes (CD8, CD4) and macrophages (ED1, ED2) in rats having had treatment of a primary tumour." (PMID 16091763, 2005). "Murine tumor-draining lymph node (TDLN) cells were segregated to purify the CD62Llow subset, or the CD4+ subset thereof." (PMID 15566571, 2004). "For this assay, a single cell digest of in vivo propagated tumor is used which contains MHC class II+ APC as well as tumor cells and is capable of stimulating both CD4+ and CD8+ T cells." (PMID 15566571, 2004). "We showed a lower percentage of CD3+, CD4+ and CD25+ T cells in tumours with COX-2 positive immunostaining in tumour cells suggesting that the expression of high levels of COX-2 in tumour cells can play a major role in inhibiting host immune functions." (PMID 12402155, 2002). "The identification of tumour antigens with SEREX is based on the presence of IgG autoantibodies, the formation of which relies on CD4+ T lymphocytes (helper T cells)." (PMID 12177805, 2002). "The proportion of CD3+, CD4+, and CD25+ cells was significantly lower in tumours with high tumour/stroma cyclooxygenase-2 IDV ratio, while a higher percentage of mast cells was detected in tumours showing high tumour/stroma cyclooxygenase-2 IDV ratio." (PMID 12402155, 2002). "Lymphocyte rolling by ‘immune’ CD4+ and CD8+ T-cells in the tumour microcirculation was greatly reduced, suggesting impaired adhesion molecule expression on the tumour endothelium." (PMID 10993655, 2000). "This study clearly demonstrates, by direct in vivo microscopy assessment, the localization of effector cells, CD4+ and CD8+ lymphocytes into tumours." (PMID 10993655, 2000). "CD4+ and CD8+ T-lymphocytes prepared from the spleens of ‘tumour immune’ mice were evaluated for their ability to traffic into the tumour environment using an in vivo model that enables visualization of events within the microvasculature." (PMID 10993655, 2000). "Fluorescently labelled CD4+ and CD8+ T lymphocytes taken from the spleens of naive mice or mice previously immunized with RENCA-IL-2 were injected systemically into tumour-bearer mice." (PMID 10993655, 2000). "Therapy-induced accumulation of perforin-containing cells at the tumour site was significantly impaired in CD8 KO mice, and marginally in CD4 KO mice." (PMID 10496366, 1999). "The majority of the V beta 11-positive tumours were CD4- CD8+ and were only observed in mice showing clinical evidence of tumour development at a relatively young age." (PMID 8554976, 1996). "CaECT treatment induced systemic immune alterations across electroporation groups, including increased CD4+ and CD8+ memory T-cell populations in the spleen and reduced CD4+ regulatory T cells and myeloid-derived suppressor cells in tumor-draining lymph nodes." (PMID 42088507, 2026).
tumor (continued). "After activation of CD4+ T cells, they differentiate into Th1 cells producing IL-2 and IFN-γ, whereas CD8+ cytotoxic T lymphocytes (CTLs) synthesize granzyme and perforin to eliminate tumor cells presenting cognate antigens." (PMID 41601669, 2026). "Multicolor flow cytometry analysis of tumor-infiltrating immune cells revealed that Nat10 deletion markedly increased CD8+ and CD4+ T cell infiltration and modestly elevated the numbers of NK cells and macrophages, whereas the myeloid-derived suppressor cell populations were unaltered." (PMID 41542770, 2026). "Additionally, immune cells such as CD4+, CD8+, and M2 macrophages are key players in the tumor microenvironment, influencing treatment responses and serving as prognostic biomarkers." (PMID 41992056, 2026). "Notably, MIF is a critical factor associated with malignant cell metastasis, as it impedes the cytotoxic activity of CD4+ and CD8+ T cells against local tumor cells." (PMID 41158758, 2026). "Flow cytometry and western blot revealed that SSG can increase the proportion of CD8+ central memory T cells, reduce the proportion of CD8+ effector memory T cells, reduce the proportion of CD4+CD25+Foxp3+ Treg cells, and play a role in regulating the tumor microenvironment." (PMID 41993133, 2026). "Notably, treatment with Cu-Pic/HA NPs resulted in a 4.2-fold and 3.2-fold increase in the proportions of CD4+ and CD8+ T cells in the tumor, respectively, compared to the control group." (PMID 41424843, 2026). "Similarly, in the iron-overloaded TME, ferroptosis of activated naive CD4+ T cells 66 and CD8+ T cells 67 leads to a decrease in their numbers and a decline in their anti-tumor functions." (PMID 41355954, 2026). "In addition, Plasmodium infection reduced the expression levels of PD-1 on CD4+ and CD8+ T, the number of polymorphonuclear MDSCs, and increased the ratio of M1/M2 macrophages in the tumor tissues." (PMID 41685208, 2026). "Concurrently, the infection also increased the numbers of CD3+ T cells, including CD4+ and CD8+ T, CD4+ Tcm, CD4+ Tem, CD4+ tissue resident memory T (Trm), CD8+ Tcm, CD8+ Tem, CD8+ Trm and CD8+ SLEC in tumor tissues." (PMID 41685208, 2026). "Immunohistochemistry revealed higher expression of CD4, CD8, CD31, and PD-L1 in brain metastases compared to the primary tumor, suggesting increased T-cell infiltration and enhanced immune activity in the tumor microenvironment." (PMID 42294305, 2026). "In allogeneic graft-versus-host disease and tumor models, we demonstrate that the absence of MHC class I on target cells significantly increases their susceptibility to CD4+ T cell cytotoxicity." (PMID 41876718, 2026). "The TIMER database was used for the analysis of potential associations of the 4 CRICGs for constructing the predictive model with different types of tumor-infiltrating immune cells in the TME, including B cells, CD8+ T cells, CD4+ T cells, macrophages, neutrophils, and dendritic cells." (PMID 41560064, 2026). "We find that tumor control does not depend on CD8+ T cells or tumor cell MHC expression but instead requires IFNγ-producing CD4+ T cells (Th1s) that are primed by dendritic cells in lymph nodes." (PMID 42102812, 2026). "Finally, IL-2 from CD4 + Th1 cells, in combination with IFN-γ, promotes cell proliferation and cytotoxic activity of CD8 + CTLs and NK cells working together to kill tumor cells." (PMID 41582199, 2026). "Notably, in CC4, we observed co‐localisation of ILC2s with cells associated with tertiary lymphoid structures (TLS), including CD4+ Tfh cells, B‐CD40‐GC‐like cells and tumour cells." (PMID 41527493, 2026). "For example, cachectic mice display notable depletion of CD44low CD4+ T cells, a type of quiescent naïve cell, in lymph nodes and spleens compared with noncachectic diabetic tumor-bearing mice." (PMID 41526343, 2026).